MSH6 (mutS homolog 6)
Diseases named in the same sentence as MSH6 in open-access papers (continued):
Sharing a sentence is not in itself a finding about the gene and the disease.
Lynch syndrome (continued). "The patient’s two brothers and daughter were also found to carry the identified MSH6 mutation and were recommended to follow National Comprehensive Cancer Network guidelines for Lynch syndrome screening." (PMID 31307558, 2019). "This testing revealed that she had a heterozygous MSH6 mutation as part of the Lynch syndrome panel." (PMID 31307558, 2019). "Several MSH6 mutations have been identified and suggested as causative in Lynch syndrome (LS) patients." (PMID 31374908, 2019). "MSH6 staining is suggestive of at least one expressing MSH6 allele and therefore this case is more consistent with a possible Lynch syndrome than CMMRD despite the observed TMB results." (PMID 31604779, 2019). "This suggests that disruption of the reading frame in this gene region is pathogenic and the novel MSH6 variant likely also predisposes to Lynch syndrome." (PMID 30217226, 2018). "A third report described a case of gastric-type adenocarcinoma of the cervix in a patient with Lynch syndrome secondary to a germline mutation in the MSH6 MMR gene." (PMID 29587389, 2018). "Only two tumors (0.5%) showed tumor‐specific loss of staining for MLH1 and MSH6, respectively, suggestive of Lynch syndrome and thus have a negligible impact on the results." (PMID 29791078, 2018). "In this retrospective cohort study of 1063 individuals with proven Lynch syndrome, men and women with MSH6 mutations were diagnosed with colorectal and endometrial cancer at later ages than those with other mutations." (PMID 28772289, 2017). "Mutations in MSH6 are traditionally associated with Lynch syndrome, a syndrome that seems to encompass BC susceptibility according to recent publications." (PMID 28502252, 2017). "The index case with Lynch syndrome harbours a heterozygous mutation in the mismatch repair MSH6 gene." (PMID 27456091, 2016). "The finding of near-to-complete loss of MSH6 expression in affected men with a family history of Lynch Syndrome supports its mechanistic involvement during prostate carcinogenesis." (PMID 27456091, 2016). "Mutations in MSH6 result in defects in DNA mismatch repair and increased risk for several malignancies as was demonstrated for Lynch syndrome." (PMID 27366948, 2016). "Consistent with the evidence that MSH6 is associated with Lynch syndrome, family 3 included one grandfather who developed colorectal cancer." (PMID 26436112, 2015).
Lynch syndrome (continued). "About 24% of the mutations identified in Lynch syndrome are missense substitutions and the frequency of missense variants in MSH6 is the highest amongst these MMR genes." (PMID 23621914, 2013). "A metastatic ACC of the pancreas was described in a female patient carrying a mutation in MSH6, one of the genes responsible for the Lynch syndrome." (PMID 23374397, 2013). "A common finding in several studies of MSI in Lynch syndrome endometrial tumours has been a lower frequency of MSI in tumours from MSH6 mutation carriers." (PMID 24056992, 2013). "We recreated three MSH6 variants found in suspected Lynch syndrome families, MSH6-P1087R, MSH6-R1095H and MSH6-L1354Q, and found all three to behave like wild type MSH6." (PMID 24040339, 2013). "Approximately 10 percent of Lynch syndrome families have a mutation in MSH6 and fewer families have a mutation in PMS2." (PMID 20487569, 2010). "The identified MSH6 mutations represent 10.3% of the pathogenic mutations identified in MMR genes in our Lynch syndrome families." (PMID 20487569, 2010). "Together with improvements in technology the ability to rapidly screen additional genes associated with Lynch syndrome, MSH6 and PMS2, has become available." (PMID 20487569, 2010). "Germline mutations in MSH6 are relatively rare and estimated to account for 5–10% of Lynch syndrome cases." (PMID 21081928, 2010). "This is in accordance with the expected frequencies of MSH6 mutations in already published material on Lynch syndrome." (PMID 20487569, 2010). "Furthermore, a 3-year surveillance interval is more cost-effective for patients who have Lynch syndrome with MSH6 or PMS2 as the causative gene." (PMID 41214301, 2026). "Here, we diagnosed three new cases of Lynch syndrome, two of whom had MSH6 pathogenic variants." (PMID 41138669, 2025). "Moreover, high discordant results (36%) using IHC and MSI were observed, especially for MSH6 variant carriers in Lynch syndrome–associated tumors." (PMID 40880425, 2025). "For MSH6 c.133G > C (p.Gly45Arg), 3 submissions were found in ClinVar, all of which were germline mutations from patients with Hereditary cancer-predisposing syndrome or Lynch syndrome (National Center for Biotechnology Information." (PMID 38297350, 2024).
Lynch syndrome (continued). "Lynch syndrome (LS) may result from these genes, with MMR gene mutations being prevalent in BC patients, according to studies, Lynch syndrome (LS) might arise from mutation in MSH6 and common in BC patients." (PMID 39390525, 2024). "Hence, although no CPS clinical screening criteria were fulfilled we established the diagnosis of a Lynch syndrome due to the de novo MSH6 variant." (PMID 33840814, 2021). "A 67-year-old man with Lynch syndrome (MSH6 mutation) and polycythemia vera presented with histologically-proven MCC (unknown Merkel cell polyomavirus (MCPyV) status) metastatic to the liver." (PMID 31287031, 2019). "However, constitutional testing identified only one nonsense MSH6 variant consistent with a Lynch syndrome diagnosis." (PMID 31604779, 2019). "Using MSI burden and bi-allelic alteration status, we reclassify two variants of unknown significance in MSH6 as potentially pathogenic for Lynch syndrome." (PMID 30217226, 2018). "The two genetic mutations recorded were of BRCA1/2 and MSH6 causing Lynch syndrome." (PMID 30309438, 2018). "We also found 1 patient with a pathogenic mutation in MSH6 gene, associated to Lynch syndrome, a colorectal cancer syndrome whose correlation with BC is still debated: this finding will allow for appropriate genetic counseling and the extension of the genetic test to the relatives." (PMID 28423363, 2017). "The mutation of MSH6 only accounts for a small portion of Lynch syndrome." (PMID 28699072, 2017). "However, this study was limited by our inability to test other MMR gene germline mutations associated with Lynch syndrome, including MSH6, PMS2, and EPCAM germline mutations." (PMID 27907203, 2016). "Similarly, in FAP5 the presence of MSH6 c.663A > C (p.E221D) was identified, this variant has been related to Lynch syndrome although it is of uncertain clinical significance." (PMID 26300997, 2015). "In addition, this study was limited by our inability to test for other MMR gene germline mutations that are also associated with Lynch syndrome, such as MSH6, PMS2 and EPCAM germline mutations." (PMID 26053027, 2015). "The apparent difference in tumour spectrum between carriers of the POLE p.Leu424Val and the POLD1 p.Ser478Asn substitutions was unexplained and the authors mention that similar differences are found in Lynch syndrome where endometrial cancer seems to be more frequent in carriers of MSH6 mutations." (PMID 24788313, 2014). "It will be of interest to determine whether the entire panel of rare MSH6 Lynch Syndrome alleles confers a dominant negative function as has been previously reported for a variant of MSH6." (PMID 23821616, 2013). "Since it is unlikely that the MSH6 mutation represents a de novo mutation, the low frequency of Lynch Syndrome associated cancers in both branches of the family may be due to reduced penetrance of MSH6 mutations." (PMID 23164213, 2012). "A meta-analysis of 5 different MSH6 mutation positive Lynch syndrome cohorts displayed a much lower lifetime risk of CRC at ~20%, which is an indication that our sample cohort might be too small to produce reliable lifetime risk figures." (PMID 20487569, 2010). "Similarly, the germline MSH6 variants are related to Lynch syndrome and CMMRD." (PMID 40995433, 2025).
Lynch syndrome (continued). "A verified Lynch syndrome mutation was identified in the patient’s mother in 2015 and was subsequently confirmed in the patient with diagnosis of the poorly differentiated invasive ductal BC; it is a heterozygous mutation of the mismatch repair gene MSH6: c.2690dupA/p.Asn897LysfsTer3." (PMID 36755294, 2023). "Finally, we identified a hypermutated patient with cHL and discovered a mutation in MSH6 that is similar in kind and location to other variants associated with Lynch syndrome, which could be driving the patient's hypermutated phenotype." (PMID 37910143, 2023). "Furthermore, this germline variant has been previously identified in our laboratory in another six index patients presenting clinical criteria for Lynch Syndrome, who also showed consistent MSH6 loss of expression in their tumors, allowing the classification of this variant as likely pathogenic." (PMID 33008098, 2020). "We report a unique case of early‐onset colorectal cancer with both a germline MSH6 variant and constitutional mosaic MLH1 epimutation, revealing a possible digenic mechanism underlying Lynch syndrome." (PMID 41347766, 2026). "In our study, we identified one carrier of a pathogenic variant in a Lynch Syndrome gene as having HPV‐negative adenocarcinoma of the cervix and a variant in MSH6." (PMID 39440754, 2025).
Lynch syndrome (continued). "MSH6 is listed as a disease gene for Lynch syndrome and familial endometrial cancer, both of which are diseases with autosomal dominant transmission." (PMID 40862798, 2025). "MSH6 sequencing identified c.3261del (p.Phe1088Serfs*2), leading to a diagnosis of Lynch syndrome, and genetic counseling was provided." (PMID 39186128, 2024).